LINC02535 (long independently transcribed non-coding RNA 2535)
Gene: Long non-coding RNA gene on chromosome 6 (85,320,314 to 85,404,911, reverse strand). Ensembl gene ENSG00000234155.
Diseases named in the same sentence as LINC02535 in open-access papers:
LINC02535 is named in the same sentence as 4 diseases in open-access papers, as found by Europe PMC text mining. Sharing a sentence is not in itself a finding about the gene and the disease. The quoted sentences say what the papers report.
gastric cancer (1 paper, 2024). A primary or metastatic malignant neoplasm involving the stomach. "Therefore, to validate our bioinformatics findings, we performed RT-qPCR to determine the expression levels of LINC02086 and LINC02535, which demonstrated a substantial up-regulation of their expression in gastric cancer cells, aligning with our bioinformatics prediction." (PMID 38370380, 2024).
lung carcinoma (1 paper, 2025). "Furthermore, LINC02535 is upregulated in lung cancer and acts as a sponge by inhibiting miR-30a-5p, which, interestingly, is downregulated in serum and liver tissue of HCC patients." (PMID 40699747, 2025).
tumor (1 paper, 2021). "Knocking down LINC02535 also significantly inhibited the EMT, a key contributor to tumor invasion and metastasis, by inducing the expression of SNAIL, MMP2, and CDH2 (N-cadherin)." (PMID 33869203, 2021).
LINC02535 also shares sentences with these, for which no sentence is quoted: cancer (1 paper).